TRIM14 (tripartite motif containing 14)
Description:
Plays an essential role in the innate immune defense against viruses and bacteria. Promotes the 'Lys-48'-linked ubiquitination and subsequent degradation of hepatitis C virus NS5A leading to the inhibition of viral replication. Also plays a role in the inhibition of ebolavirus infection by enhancing IFN-beta and NF-kappa-B activation after binding to the viral protein NP. Facilitates the type I IFN response by interacting with MAVS at the outer mitochondria membrane and thereby recruiting NF-kappa-B essential modulator IKBKG/NEMO to the MAVS signalosome, leading to the activation of both the IFN regulatory factor 3/IRF3 and NF-kappa-B pathways. Positively regulates the CGAS-induced type I interferon signaling pathway by stabilizing CGAS and inhibiting its autophagic degradation. Acts as a scaffold between TBK1 and STAT3 to promote phosphorylation of STAT3 and resolve interferon-stimulated gene (ISG) expression. Inhibits the transcriptional activity of SPI1 in a dose-dependent manner (By similarity). Also inhibits OPTN-mediated selective autophagic degradation of KDM4D and thereby negatively regulates H3K9me2 and H3K9me3. Mechanistically, recruits USP14 to remove the 'Lys-63'-linked ubiquitination of KDM4D, preventing its recognition by OPTN and subsequent degradation.
Synonyms: KIAA0129
Tractability: PROTAC: UniProt records ubiquitination sites on it; ubiquitination databases record sites on it; its protein half-life has been measured.
Gene: Protein-coding gene on chromosome 9 (98,068,968 to 98,119,399, reverse strand). Ensembl gene ENSG00000106785.
Subcellular location: Mitochondrion outer membrane; Cytoplasmic vesicle, phagosome; Nucleus
Pathways (Reactome):
Immune System: Interferon gamma signaling
Gene Ontology:
Molecular function: molecular adaptor activity; protein binding; transcription coactivator activity; ubiquitin protein ligase activity; zinc ion binding
Biological process: antiviral innate immune response; inflammatory response; innate immune response; positive regulation of DNA-templated transcription
Cellular component: cytoplasm; mitochondrial outer membrane; nucleus; phagocytic vesicle
Genetic constraint (gnomAD): Loss-of-function variants: 30 observed, 38.33 expected, observed/expected ratio (o/e) 0.78, 90% interval 0.58 to 1.06. The synonymous counts are far from expectation, so gnomAD's model fits this gene poorly and the ratio says little. Missense variants: 607 observed, 531.52 expected, observed/expected ratio (o/e) 1.14, 90% interval 1.07 to 1.22. Synonymous variants: 299 observed, 231.9 expected, observed/expected ratio (o/e) 1.29, 90% interval 1.17 to 1.42.
Homologues: Orthologues: chimpanzee TRIM14 (97% identical), macaque TRIM14 (95% identical), rabbit TRIM14 (83% identical), pig TRIM14 (82% identical), dog TRIM14 (81% identical), mouse Trim14 (77% identical), rat Trim14 (75% identical), tropical clawed frog trim14 (49% identical). Paralogues in human: TRIM39 (22% identical), TRIM11 (21% identical), TRIM27 (20% identical), TRIM41 (20% identical), TRIM6 (20% identical), TRIM7 (20% identical), TRIM21 (20% identical), TRIM16 (19% identical), TRIM58 (19% identical), TRIM69 (19% identical), TRIM15 (18% identical), TRIM25 (18% identical), and 68 more.
Diseases named in the same sentence as TRIM14 in open-access papers:
TRIM14 is named in the same sentence as 57 diseases in open-access papers, as found by Europe PMC text mining. Sharing a sentence is not in itself a finding about the gene and the disease. The quoted sentences say what the papers report.
viral infection (15 papers, 2016 to 2025). "Upon viral infection, TRIM14 undergoes K63-linked self ubiquitination at K365, consequently recruiting NEMO to MAVS signalosome for NFκB activation." (PMID 33670221, 2021). "Upon viral infection, TRIM14 undergoes Lys-63-linked polyubiquitination at lys-365 and recruits NF-κB essential modulator to the MAVS signalosome, leading to the activation of both IRF3 and NF-κB pathways." (PMID 28211536, 2017). "Subsequent research has highlighted TRIM14’s involvement in various biological processes, including cell proliferation, apoptosis, tumor suppression, cancer progression, innate immunity, and viral infection." (PMID 40435148, 2025). "Potentially, the higher expression of duck TRIM14 in the lung and liver is a conserved protective mechanism that allows a quick response to viral infections from RNA viruses such as IAV and DHV." (PMID 37622121, 2023). "TRIM14 encodes a protein belonging to TRIM family, which are also known to promote host defense against virus infections." (PMID 36941576, 2023). "Additional studies revealed that TRIM14, which was a mitochondrial adapter that promotes innate immune signal transmission, participated in host defenses against viral infection." (PMID 35962353, 2022). "TRIM14 was recently reported as a key molecule in the IFN-signaling pathway that regulates IFN production in response to viral infection." (PMID 30150992, 2018). "Importantly, Zhou and colleague demonstrated that TRIM14 acts as a mediator in immune responses against viral infection by activating NF-κB pathways by recruiting NF-κB essential modulator (NEMO) to the MAVS signalosome." (PMID 26799420, 2016). "Interestingly, upon viral infection, TRIM14 can link NEMO to the mitochondrial antiviral signalosome and further activate the NEMO–IKK α–IKK β complex, which phosphorylates IκBα, to drive its ubiquitination and proteasomal, allowing the subsequently activation of NF-κB signaling." (PMID 26799420, 2016). "However, the involvement of TRIM14 in host defense against viral infection and molecular mechanisms remain unclear." (PMID 27578425, 2016). "TRIM14 was recently reported to play an important role in IFN and NF-κB activation during viral infection." (PMID 28002492, 2016). "TRIM14, a member of tripartite motif (TRIM) family, has been demonstrated to possess a strong capability of regulating type I interferon and NF-κB induction in host defense against viral infection." (PMID 30873142, 2019). "However, the mechanism by which IFN-1 induces TRIM14 in response to viral infection is not well characterized." (PMID 30150992, 2018). "Since TRIM14 is a multifunctional protein, we could not exclude the possibility that TRIM14 other domain interacts with IAV proteins to promote viral infection and negatively regulate the anti-IAV effect of TRIM14." (PMID 30873142, 2019).
gastric cancer (13 papers, 2020 to 2025). A primary or metastatic malignant neoplasm involving the stomach. "Furthermore, TRIM14 expression was regulated by miR-195-5p, and its overexpression was linked to lower miR-195-5p levels in gastric cancer tissues." (PMID 39768197, 2024). "Conversely, MicroRNA-559 suppresses gastric cancer progression by promoting AKT signaling activation through TRIM14 targeting." (PMID 40936722, 2025). "As previously discussed, TRIM14 drives gastric cancer cell migration and invasion via AKT signaling activation, with its activity under the regulation of miR-195-5p." (PMID 40936722, 2025). "TRIM14 facilitates gastric cancer cell migration and invasion by modulating epithelial-to-mesenchymal transition (EMT) through AKT signaling activation, a process regulated by miR-195-5p." (PMID 40936722, 2025). "circ_0091741 blocks the binding of miR-330-3p to TRIM14, increases TRIM14 expression, further activates the Wnt/β-catenin signaling pathway by stabilizing Dvl2, enhances gastric cancer cell autophagy and antioxidant capacity." (PMID 39703839, 2024). "In gastric cancer, overexpression of TRIM14 enhanced aggressiveness by promoting EMT and metastasis in MKN45 and SGC7901 cells." (PMID 39768197, 2024). "For instance, TRIM14 expression is elevated in diverse cancers, such as gastric cancer and cervical cancer." (PMID 37628777, 2023). "MiR-195-5p can downregulate the expression of TRIM14 and then promote the progression of gastric cancer by regulating the epithelial–mesenchymal transition process." (PMID 35652045, 2022). "TRIM65 knockdown inhibits autophagy of A549/DDP cells through the miR-138-5P/ATG7 pathway, whereas TRIM14 promotes autophagy in gastric cancer cells by activating the AMPK pathway." (PMID 36587218, 2022). "Overexpression of TRIM14 promoted gastric cancer cell invasion and epithelial-mesenchymal transition." (PMID 33982666, 2021). "In gastric cancer, TRIM14 was aberrantly upregulated in cancer tissues and cell lines." (PMID 33982666, 2021). "Moreover, TRIM14 expression were found upregulated in gastric cancer." (PMID 35962353, 2022). "TRIM14 was overexpressed in gastric cancer tissues and OXA-resistant human gastric cancer cells, HGC-27/OXA." (PMID 39768197, 2024). "In gastric cancer cells resistant to 5-FU and OXA, TRIM14 was found to be overexpressed, whose oncogenic effect was mediated by triggering the AMPK/mTOR pathway." (PMID 39768197, 2024). "Previous studies have also indicated that TRIM14 is upregulated in 5-FU- and L-OHP-resistant gastric cancer tissues and cells." (PMID 37628777, 2023). "Interestingly, the authors identified TRIM14 as a direct target of miR-195-5p in GC and confirmed an inverse correlation between TRIM14 mRNA and miR-195-5p in gastric cancer tissues." (PMID 33066016, 2020). "In a similar way, upregulation of TRIM14 via induction of Akt signaling promotes migration and invasion and EMT progression of gastric cancer." (PMID 33066016, 2020). "The targeted inhibition of miR-195-5p on TRIM14 was reported in OSCC and gastric cancer." (PMID 35087744, 2021). "A previous study reported that overexpression of TRIM14 promotes p-AKT, p-mTOR, and p-P70S6K expression, while TRIM14 knockout induces opposite effects; furthermore, AKT inhibition has been demonstrated to counteract the pro-migratory and pro-invasive effects of TRIM14 in gastric cancer cells." (PMID 40936722, 2025).
colorectal cancer (12 papers, 2018 to 2025). A primary or metastatic malignant neoplasm that affects the colon or rectum. "For example, in the hypoxic microenvironment of tumors, high expression of TRIM14 in colorectal cancer (CRC) significantly suppresses CRC cell apoptosis and promotes CRC cell proliferation and invasion." (PMID 39667820, 2024). "Overexpressed TRIM14 can bolster breast cancer cell proliferation, adding to the malignancy of colorectal cancer." (PMID 37628777, 2023). "The STAT3 pathway has been shown to participate in the promotion of colorectal cancer cell invasion induced by TRIM14." (PMID 33982666, 2021). "For instance, TRIM14 accelerated the migration and invasion abilities of colorectal cancer cells through regulating SPHK1/STAT3 signaling." (PMID 33892646, 2021). "TRIM14 has been reported to promote invasion in glioblastoma and colorectal cancer." (PMID 31861273, 2019). "In colorectal cancer, miR-191-5p acts as a tumor suppressor because its endogenous induction inhibits cell proliferation and invasion through two molecular targets: special AT-rich sequence-binding protein 1 (SATB1) and tripartite motif-containing 14 (TRIM14)." (PMID 38994952, 2024). "In addition, elevated TRIM14 levels can localize PTEN to the cytoplasm and induce polyubiquitination to degrade it in colorectal cancer, thereby triggering AKT signaling." (PMID 39768197, 2024). "Additionally, TRIM14 represses the expression of phosphatase and tensin homology (PTEN) in colorectal cancer." (PMID 34787066, 2022).
glioma (12 papers, 2018 to 2025). A benign or malignant brain and spinal cord tumor that arises from glial cells (astrocytes, oligodendrocytes, ependymal cells). "In conclusion, TRIM14 is significantly upregulated in gliomas, and high expression is closely associated with poor prognosis in patients." (PMID 41463095, 2025). "To further explore the clinical significance of ATP7A in glioma and its relationship with TRIM14, we first conducted an analysis using public databases." (PMID 41463095, 2025). "Using TCGA and CGGA databases, we found that TRIM14 is highly expressed in gliomas, and patients with high TRIM14 expression have a poor survival rate." (PMID 41463095, 2025). "To further clarify the role of TRIM14 in TMZ+CuCl2-induced cuproptosis, we knocked down TRIM14 in glioma cells." (PMID 41463095, 2025). "This study reveals the important role of TRIM14 in glioma and systematically elucidates the potential function of the TRIM14–ATP7A axis in copper homeostasis regulation and cuproptosis." (PMID 41463095, 2025). "This study first reveals the possible mechanism by which TMZ and copper ions induce cuproptosis through targeting the TRIM14–ATP7A axis and emphasizes the potential value of TRIM14 in the prognosis evaluation and treatment of glioma." (PMID 41463095, 2025). "lncRNA CHASERR sequesters miR-6893-3p and positively regulates TRIM14 expression, thereby promoting glioma growth." (PMID 38967893, 2024). "TRIM14 expression is low in normal brain tissue and high in glioma specimens, especially in GBM specimens, and its high expression also implies a poor prognosis." (PMID 39719450, 2024). "The TRIM14 expression levels correlated positively with the glioma malignancy grade and were indicative of a poor clinical outcome." (PMID 36139694, 2022). "In glioma, TRIM14 was overexpressed in tumor tissues and cell lines, and TRIM14 levels were negatively correlated with the survival time of glioma patients." (PMID 33982666, 2021). "Our results suggested that TRIM14 expression was altered by miR-198 on the progression of TMZ-resistant glioma cells." (PMID 33316781, 2020). "TRIM14 not only plays a role in copper homeostasis regulation and resistance mechanisms in glioma but may also influence treatment outcomes by affecting the cuproptosis pathway." (PMID 41463095, 2025). "For example, downregulating TRIM14 expression may enhance the antitumor effects of TMZ+CuCl2 co-treatment in gliomas, while avoiding TRIM14′s promotion of resistance through the maintenance of high ATP7A expression." (PMID 41463095, 2025). "To assess the clinical relevance of TRIM14 in glioma, we first analyzed the TCGA database." (PMID 41463095, 2025). "We found that high expression of TRIM14 may enhance glioma cell resistance by promoting the upregulation of ATP7A, reducing copper accumulation, and inhibiting cuproptosis." (PMID 41463095, 2025). "In addition, TRIM14 can promote glioma progression by activating the Akt/mTOR/P70S6K and Wnt/β-catenin signaling pathways." (PMID 39719450, 2024). "TRIM14 elevated the drug resistance of glioma cells through regulating Wnt/β-catenin signaling." (PMID 33892646, 2021). "Moreover, TRIM14 also participated in regulating glioma chemoresistance and epithelial-mesenchymal transition." (PMID 33982666, 2021). "TRIM14 promoted epithelial-mesenchymal transition in glioma cells." (PMID 33982666, 2021). "We showed that TRIM14 expression was required to maintain TMZ resistance in glioma cells." (PMID 33316781, 2020). "We investigated the impacts exerted by TRIM14 on TMZ resistance of glioma." (PMID 33316781, 2020). "Investigations have been reported on the involvement of TRIM14 in glioma chemoresistance." (PMID 33316781, 2020). "However, the precise molecular mechanisms by which TRIM14 functions in glioma remain unclear and warrant further investigation." (PMID 41463095, 2025). "Therefore, targeted modulation of TRIM14 may be an effective strategy for ameliorating drug resistance in glioma." (PMID 39719450, 2024).
glioma (continued). "Besides, TRIM14 facilitated epithelial-mesenchymal transition and chemoresistance of glioma." (PMID 33316781, 2020). "Furthermore, TRIM14 over-expression could invert the inhibiting effect of miR-198 on the progression of TMZ-resistant glioma cells, thereby confirming that TRIM14 functioned as a target gene of miR-198." (PMID 33316781, 2020). "Hence, TRIM14 was expected to be a good target for glioma treatment." (PMID 33316781, 2020). "This study aimed to investigate the role of tripartite motif-containing protein 14 (TRIM14) and its downstream effector ATP7A in mediating TMZ- and copper-induced cuproptosis in glioma." (PMID 41463095, 2025). "The interplay among lncRNA CHASERR, miR-6893-3p, and TRIM14 can activate the PTEN/p-Akt/mTOR and Wnt/β-catenin pathways to regulate glioma growth." (PMID 38967893, 2024). "Several cancer-related signaling pathways are reportedly activated by TRIM14, such as the AKT pathway in osteosarcoma, the NF-κB pathway in tongue squamous cell carcinoma, and the Wnt/β-catenin pathway in glioma." (PMID 34787066, 2022). "TRIM24, TRIM47, TRIM44, TRIM31, TRIM14, TRIM21, and TRIM28 have exhibited significant prognostic value regarding OS and/or PFS of glioma patients." (PMID 36139694, 2022). "Taken together, our study revealed that circ_0005198 exerted its function as a ceRNA through sponging miR-198 to regulate TRIM14 expression, and therefore contributed to TMZ resistance in glioma." (PMID 33316781, 2020). "Our study verified that TRIM14 was highly expressed in glioma and its silencing inhibited the progression of TMZ-resistant glioma cells." (PMID 33316781, 2020). "In line with our findings, previous studies have reported the overexpression of TRIM14 in HCC, OSCC, TSCC, osteosarcoma, glioma and breast cancer." (PMID 30555277, 2018). "Several cancer-related signaling pathways have been reported to be activated by TRIM14, such as AKT pathway in osteosarcoma, NF-κB pathway in TSCC, Wnt/β-catenin pathway in glioma and STAT3 in breast cancer." (PMID 30555277, 2018). "Further mechanistic studies suggest that TRIM14 may regulate ATP7A protein levels through interaction, highlighting the potential role of the TRIM14–ATP7A axis in copper homeostasis and glioma progression." (PMID 41463095, 2025). "TRIM14 was highly expressed in glioma tissues and TMZ-resistant glioma cells." (PMID 33316781, 2020). "Moreover, TRIM14 was a target of miR-198 and silencing of TRIM14 hindered TMZ resistance and suppressed the progression of TMZ-resistant glioma cells, while TRIM14 over-expression rescued the inhibiting effect of miR-198 over-expression." (PMID 33316781, 2020).